SYN2 (synapsin II)
Diseases named in the same sentence as SYN2 in open-access papers (continued):
Sharing a sentence is not in itself a finding about the gene and the disease.
infantile spasms (1 paper, 2020). A rare epilepsy syndrome characterized by onset of epileptic spasms in infants between 2 and 12 months of age, and rarely up to 24 months. "In addition, the two patients with SYN2 and MAGI1 variations in our datasets experienced infantile spasms." (PMID 33584793, 2020).
leprosy (1 paper, 2016). Leprosy is a chronic infectious disease affecting primarily the skin and peripheral nervous system. "We confirmed all the known leprosy susceptibility loci and identified four novel loci on 3p25.2 (SYN2), 7p14.3 (BBS9), 8p23.1 (CTSB) and 8q24.11 (MED30)." (PMID 27976721, 2016). "At 3p25.2, we identified a non-coding variant nearby PPARG and SYN2 that were both significantly down regulated in the lesion of leprosy patients." (PMID 27976721, 2016). "Interestingly, the expression SYN2 was also down-regulated in the leprosy biopsy in our study, which may suggest its role in the infection progress of mycobacteria to the nerves." (PMID 27976721, 2016). "The SNP rs6807915 located between SYN2 and PPARG gene, which were significantly down regulated in the lesion of leprosy patients." (PMID 27976721, 2016).
partial epilepsy (1 paper, 2014). "We sequenced the coding and splicing junction regions of SYN2 in 190 cases with ASD and 143 cases with partial epilepsy." (PMID 23956174, 2014).
RSV bronchiolitis (1 paper, 2023). "The medians of the transcription levels of HERV-H-pol, HERV-K-pol, and HERV-W-pol, as well as of SYN1-env and SYN2-env, were significantly lower in children with RSV bronchiolitis as compared to HC." (PMID 36826024, 2023). "Present results highlight, for the first time, that in children hospitalized for acute RSV bronchiolitis, the transcriptional levels of pol genes of HERV-H, -K, and -W, as well as of env genes of SYN1 and SYN2 were significantly lower than in HC." (PMID 36826024, 2023).
status epilepticus (1 paper, 2015). Status epilepticus is defined as a continuous seizure lasting more than 30 min, or two or more seizures without full recovery of consciousness between any of them. "The increase in CX3CR1 in Syn2-/- mice is in line with our recent findings following electrically-induced status epilepticus in rats." (PMID 26177381, 2015). "Status epilepticus is a more severe seizure model than the handling-induced seizures in the Syn2-/- mice, which may explain why we, in the current study, did not detect a strong seizure-induced increase in CX3CR1 expression in the tonic-clonic phase." (PMID 26177381, 2015).
temporal lobe epilepsy (1 paper, 2023). A localization-related (focal) form of epilepsy characterized by recurrent seizures that arise from foci within the temporal lobe, most commonly from its mesial aspect. "To this aim, we used the Synapsin II knockout (SynIIKO) mouse, a model of temporal lobe epilepsy in which seizures manifest 2–3 months after birth, offering a temporal window in which LGID may affect epileptogenesis." (PMID 37947886, 2023).
cancer (4 papers, 2010 to 2023). A tumor composed of atypical neoplastic, often pleomorphic cells that invade other tissues. "Interestingly, another cancer-associated gene, TIMP4, located within an intron of SYN2 and transcribed in the opposite direction, was found to interact with folic acid supplement use and alter risk of CRC." (PMID 37640106, 2023). "The relationship between Syn2 and cancer has not yet been reported and needs to be clarified in future studies." (PMID 23451142, 2013).
infection (4 papers, 2014 to 2023). The state of being infected such as from the introduction of a foreign agent such as serum, vaccine, antigenic substance or organism. "Along these lines, we observed that the serum levels of the EAE onset-leading NDICPs showed that the levels of GS and SYN2 remained relatively unaffected by adjuvants and infection, whereas ENO2 and SYT1 expression was more susceptible to modulation by these confounding factors." (PMID 28769926, 2017). "Our results also suggested that the interaction of Gal-1 with Syn-2-pseudotyped viruses maximized the interaction between Syn-2 and MFSD2a, as the effect was only observable during the early phase of infection." (PMID 38140682, 2023). "We previously established a link between Syn-2 and Gal-1 using Syn-2-pseudotyped viruses and showed that the addition of recombinant Gal-1 during the infection of HEK293T cells significantly increases the infectivity of pseudotyped viruses." (PMID 38140682, 2023). "In the present study, we extend this association in different cell lines and provide evidence that, using cell fusion and infection assays, Gal-1 increased the binding of Syn-2 with MFSD2a, likely by binding two both cell surface proteins and creating a bridge." (PMID 38140682, 2023). "Conversely, the overexpression of VASH2 by the AdVASH2 infection augmented the fusion of BeWo cells without any changes in the expression of Gcm-1, Syn-1, and Syn-2." (PMID 25184477, 2014). "Importantly, the AdVASH2 infection did not alter the expression of Gcm-1, Syn-1 and Syn-2 in BeWo cells." (PMID 25184477, 2014). "Moreover, levels of GS and SYN2 were not affected by infection with C. muridarum." (PMID 28769926, 2017).
neurodegenerative disease (4 papers, 2019 to 2024). A disorder of the central nervous system characterized by gradual and progressive loss of neural tissue and neurologic function. "The results showed that the single-cell samples of the CA1 subregion were mainly involved in vesicle-mediated transport in synapse and neurodegenerative disease-related functions, and Syn2, Sh3gl2, Aldoa, Tubb2a and Eno1 were screened as the key target genes." (PMID 36768134, 2023).
tumor (3 papers, 2013 to 2022). "Another five genes that were up-regulated with tumor progression showed further increased expressions after chemotherapy (CRISP3, KCNMA1, BDNF, SLC22A4, SYN2)." (PMID 23451142, 2013). "SYN2 and MAPT were overexpressed in all tumor samples compared to normal samples." (PMID 35252219, 2021).
psychiatric disease (2 papers, 2015 to 2017). "Of these SYN1, SYN2, and SYN3 are all associated with psychiatric disease, and the synaptic transmission and synaptic vesicle trafficking pathway." (PMID 26399914, 2015).
digestive system tumors (1 paper, 2021). "The expression analysis of LLPS regulatory factors showed that a variety of LLPS regulatory factors were significantly dysregulated in digestive system tumors, such as syn2 and MAPT." (PMID 35252219, 2021). "Of these PPLS, only two proteins were found to be dysregulated in all four digestive tumors, including syn2 and MAPT." (PMID 35252219, 2021).
immune dysfunctions (1 paper, 2022). "The aberrant expression of HERV elements, in particular of SYN1, SYN2, and MSRV, in ASD children might thus contribute to their immune dysfunctions and to the inflammatory and autoimmune-driven brain damage." (PMID 35682642, 2022).
SYN2 also shares sentences with these, for which no sentence is quoted: bipolar disorder (4 papers); autism spectrum disorder (3); Epileptic Seizures (2); nervous system diseases (2); benign meningioma (1); cardiovascular disease (1); Crohn disease (1); diabetes mellitus (1); food allergy (1); glioma (1); Hypertension (1); Intellectual disability (1); learning disorders (1); metastatic melanoma (1); movement disorder (1); neurodevelopmental disorder (1); osteoporosis (1); prion disease (1); prostate carcinoma (1); type 2 diabetes (1); ulcerative colitis (1); virus infection (1); Visual impairment (1); vitiligo (1).